RN7SL278P (RNA, 7SL, cytoplasmic 278, pseudogene)
Gene: Miscellaneous RNA gene on chromosome 15 (76,976,915 to 76,977,210, reverse strand). Ensembl gene ENSG00000243365.
Homologues: Orthologues: chimpanzee Metazoa_SRP (99% identical), macaque Metazoa_SRP (90% identical). Paralogues in human: RN7SL1 (88% identical), RN7SL3 (87% identical), RN7SL2 (86% identical), RN7SL566P (85% identical), RN7SL678P (83% identical), RN7SL14P (83% identical), RN7SL220P (83% identical), RN7SL126P (82% identical), RN7SL230P (82% identical), RN7SL47P (82% identical), RN7SL296P (82% identical), RN7SL664P (82% identical), and 702 more.